TNF (tumor necrosis factor)
Diseases named in the same sentence as TNF in open-access papers (continued):
Sharing a sentence is not in itself a finding about the gene and the disease.
tumor (continued). "Factors such as impaired liver function, chronic liver inflammation, fibrosis, cirrhosis, increased systemic inflammation, tumor-associated cytokines (e.g., IL-6, TNF-α), tumor hypoxia, and elevated VWF levels in HCC may also contribute to a relative deficiency of ADAMTS13." (PMID 40699668, 2025). "Additionally, integrating TNF-α into prognostic models alongside tumor markers and inflammatory indices could improve risk stratification." (PMID 40299527, 2025). "Notably, reduced 5-HT levels have been linked to increased TNF-α and IL-6, creating a feed-forward loop between neurotransmitter imbalance and inflammation that may foster a microenvironment conducive to tumor growth and metastasis." (PMID 41480347, 2025). "The antitumor response was linked to the accumulation of M1-type macrophages in the tumor microenvironment and the overexpression of mRNA for antitumor mediators Inducible Nitric Oxide Synthase, Tumor Necrosis Factor-alpha, and Interleukin-6 (iNOS, TNF-α, and IL-6)." (PMID 40931613, 2025). "In TAMs, canonical NF-κB (RelA/p50) promotes proinflammatory cytokine production (e.g., TNF-α, IL-6) in inflammation-driven cancers (e.g., colitis-associated colon cancer) or immunosuppressive IL-10 secretion in breast and ovarian cancers, fostering tumor growth and immune escape." (PMID 40562870, 2025). "Additionally, we observed higher expression levels of pro-inflammatory cytokines, including IL-6 and TNF-α in high-risk samples, which may reflect an inflammatory state within the tumor microenvironment." (PMID 40601653, 2025). "Additionally, TNF has been implicated in the selective destruction of tumor vasculature, while paradoxically also promoting tumor progression by facilitating tissue remodeling and stromal development required for tumor dissemination." (PMID 40427207, 2025). "Additionally, Ccn1‐deficient tumor cells exhibit sensitivity to TNFα." (PMID 40287974, 2025). "Exposure to pathogen-associated molecules, such as IFN-γ, TNF-α, or LPS causes macrophages to polarize to the M1 type, which secrete abundant quantities of pro-inflammatory factors, dominate the inflammatory microenvironment unfavorable to tissue recovery, and participate in anti-tumor immunity." (PMID 39207178, 2025). "Tumor necrosis factor α (TNF-α) is a pro-inflammatory cytokine produced by both malignant and immune cells within the tumor-associated microenvironment and contributes to the development and progression of malignant disease by creating an inflammatory niche that supports the tumor." (PMID 39408920, 2024). "In addition, D609 could function as a target for tumor cell apoptosis by modulating the cytotoxicity caused by U937 cells when exposed to tumor necrosis factor (TNF) and anti‐Fas antibodies." (PMID 39692711, 2024). "However, TNF also causes cytokine dysregulation and promotes tumor inflammation." (PMID 38664743, 2024). "Furthermore, inflammatory cytokines, such as TNF-α, IL-1, and IL-6; growth factors; chemokines; and proteases secreted by tumor-associated lymphocytes and macrophages increase tumor cell proliferation, survival, migration, and invasion, thus promoting tumor growth and metastasis." (PMID 38297164, 2024). "TNF-α promotes tumor growth by causing inflammation, and it might be a target for cancer treatment." (PMID 37373025, 2023). "Indeed, mice carrying Treg-specific Ezh2 deficiency showed a reduced growth of different types of tumors (e.g., CRC, melanoma, prostate cancer) in association with the reprograming of tumor-infiltrating Tregs in anti-tumor effector cells (e.g., IL-2, IFNγ, and TNF)." (PMID 36900330, 2023). "Benign imaginal disc tumours driven by mutations in the polarity factors dlg, lgl and scrib appear to activate a similar inflammatory response, with recruited haemocytes secreting Eiger (Drosophila TNFα), which triggers tumour cell apoptosis through JNK signalling." (PMID 36899813, 2023).
tumor (continued). "Various categories of cytokines are implicated in tumor development, progression, and metastasis, mainly including interleukins (ILs), interferons (IFNs), chemotactic cytokines (chemokines), growth factors, and some members of the tumor necrosis factor (TNF) superfamily." (PMID 36790566, 2023). "When exposed to the tumor microenvironment for a long time, the balance is broken and the inhibition signal is enhanced, leading to T cell depletion, and loss of proliferation, secretion of cytokines (including IL-2, TNF, and IFNγ), and degranulation by T cells." (PMID 35770416, 2023). "Therefore, TNF-α was excluded from the causative factors for tumor-induced osteoclastogenesis." (PMID 36614130, 2022). "Increased TNF-α signaling enhances the pro-oncogenic signaling pathways in epithelial cells through the Wnt/β-catenin pathway and NF-kB pathways, exacerbating the effects of proinflammatory cytokines in cancer-associated inflammation, especially IL-1β and IL-6, and accelerating tumor growth." (PMID 35884974, 2022). "Moreover, circUHRF1 was found to inhibit IFN-γ and TNF-α secretion by NK cells and high levels of plasma exosomal circUHRF1 is closely associated with a decreased proportion of NK cell and their decreased infiltration into tumor microenvironment." (PMID 35031075, 2022). "Also, the apoptosis-inducing ligand associated with intra-tumor TNF-α increased significantly." (PMID 36127698, 2022). "Furthermore, scientists observed a higher amount of M2-associated mRNAs for e.g., IL-10, Arg-1, and TGFβ and the reduction of M1-associated mRNAs such as TNF-α, IL-6, and IL-12 in tumor-associated macrophages from EC specimens, in comparison to macrophages obtained from healthy specimens." (PMID 35563789, 2022). "This review will summarize the long experimental history of Tumor Necrosis Factor that caused the initial observations of a tumor necrotizing cytokine that could serve as a potential cancer treatment and discuss the current state of research into this side of the activities of Tumor Necrosis Factor." (PMID 36358688, 2022). "Other studies demonstrated that resistant exercise on the animal cancer model mitigates tumor growth, tumor grade, viable tumor area, tumor cell proliferation, and myofiber atrophy-causing cancer cachexia via attenuating some key markers such as TNF-α, IL-6, Atrogin1, and oxidative damage." (PMID 35801156, 2022). "Moreover, MTA accumulates in MTAP-deficient tumor cells, blocks the activation of macrophages and inhibits the production of TNF-α through adenosine A2 receptor and TLR receptor after LPS stimulation, which promotes the differentiation of M2 macrophages with immunosuppressive effect." (PMID 36119047, 2022). "Moreover, Th17 numbers were increased in MDS patients, with greater expansion in low-risk disease, denoting the auto-reactive, possible anti-tumor nature of the process, whereas Th22 cells were increased in high-risk disease, correlating with increased IL-6 and TNF-a." (PMID 35735633, 2022). "Nonetheless, TNFα has also been associated with tumor progression lately, and this dual activity seems to depend on its spatiotemporal availability and pleiotropic effects on the tumor microenvironment, leading even to impairment in cytotoxic CD8+ T cells within the tumor niche." (PMID 36297669, 2022). "Among the various approaches that have been pursued for this purpose, targeted delivery of TNF to the tumor-associated vessels (e.g., by fusing this cytokine with peptide or antibody ligands that recognize receptors or molecules expressed by the tumor vasculature) represents a valid strategy." (PMID 35890309, 2022).
tumor (continued). "In the tumor microenvironment, TNF-α secreted by tumor-associated M2 macrophages could increase the expression of matrix metalloproteinases (MMPs) and VEGF through the Jun-c N-terminal kinase (JNK) and nuclear factor (NF)-kB pathways to increase their invasiveness." (PMID 36118080, 2022). "However, one cannot exclude that this cytotoxic substance contained not only LTα, but also TNF, the activity described in 1975 by Lloyd Old’s group as an endotoxin-induced serum factor that could cause tumor necrosis." (PMID 33917839, 2021). "Pathogenic microorganisms and tumor cells can be eliminated by M1 macrophages by acute proinflammatory response, immune activation reaction, and cytophagy through the release of proinflammatory factors, such as NO, IL-1β, IL-6, TNF-α, and chemokines such as CCL2, CCL3, CCL5, CXCL9, and CXCL10." (PMID 34506209, 2021). "In addition, several studies have suggested that aberrant M2 macrophages induce macrophage involvement in tumor development and that the progression and TNF-α inhibitors might provoke the potential risk of oncogenesis." (PMID 34193023, 2021). "Non-uniform NF-kB signaling across the metastatic spectrum in our study is somewhat surprising and could potentially reflect altered levels of TNF-α in the microenvironment of a growing metastasis or a pre-existing ‘NF-kB’ activity associated with tumor dissemination." (PMID 33620315, 2021). "Since TNF-α up-regulated adhesion molecules and their ligands on tumor cells and endothelial cells, we wondered whether this inflammatory factor was associated with tumor cells adhesion." (PMID 34222020, 2021). "TGF-β, IL-8, TNF-α and IL-6, Colony-stimulating factor (CSF)-1, IFNs cause an alteration in Treg cell diffraction and stimulate a Treg-mediated increased expression of PD-L-1, inhibiting the anti-tumour effect of cancer-effector cells and promoting cancer immune escape." (PMID 34885253, 2021). "In addition, it has been suggested that macrophages activated by irradiation may cause radioresistance of cancer cells and facilitate tumor recurrence after radiotherapy by inducing high expression of tumor necrosis factor-α (TNF-α) and promoting angiogenesis." (PMID 34135469, 2021). "It was assumed that bacteria may initially enter tumor tissue via passive entrapment in the leaky tumor vasculature and then accumulate within the tumor owing to the strong hemorrhage caused by tumor necrosis factor-α (TNF-α) induced by bacterial infection." (PMID 34138211, 2021). "This might be attributed to TGF-β and TNF-α as major soluble factors involved in the functional alteration of tumor associated pDCs, via inhibition of IRF-7 expression and nuclear translocation in pDC after their exposure to tumor-derived supernatants or recombinant TGF-β1 and TNF-α." (PMID 32784928, 2020). "Importantly, reduced caloric intake and regular exercise have been shown to reduce the serum concentrations of IL-6, TNFα and are associated with reduced activity of tumor-promoting transcription factors, including activator protein (AP)-1, STAT3 and NF-kB in various tissues." (PMID 32825010, 2020). "In the present study, according to the results of the IHC analysis, we speculated that in patients with FOBT-positivity, local TIM (such as TAM, TNF-α, IL-6) is conducive to tumor proliferation and vascularization and is associated with adjuvant chemotherapy resistance." (PMID 33643891, 2020). "Importantly, we found that in CD68High tumors, hypoxia is associated with the expression of pro-inflammatory cytokines, such as IL1B, IL6, and TNF, previously associated with the recruitment of other anti-tumor immune cells, suggesting the establishment of a pro-inflammatory TM." (PMID 32231135, 2020). "Therefore, low levels of TNF-α increase tumor growth, induce angiogenesis of several tumors in mice, and stimulate a sub-population of tumor-associated myeloid cells and the coexpression of endothelial and myeloid markers with pro-angiogenic/pro-vascular properties." (PMID 32283655, 2020).
tumor (continued). "TNF-α was originally described as a circulating factor that could cause tumor necrosis." (PMID 31463223, 2019). "Moreover, TNF-α is implicated in tumor growth, metastasis, and angiogenesis process." (PMID 31726654, 2019). "Based on these findings, we assume that elevated TNF-α levels can reduce the MM risk by improving immune surveillance and eliminating tumor cells, but in individuals who have already developed MM, the elevated TNF-α level may have unfavorable effects associated with shorter survival time." (PMID 30600678, 2019). "In addition to promoting tumorigenesis, inflammatory cells such as tumor-associated macrophages (TAMs) and the factors they release (IL-1, TNF-α) are known to support all of the steps in the invasion and metastasis process, and thus such cells are known to induce EMT." (PMID 31133667, 2019). "In addition, the TNF-α is secreted by macrophages associated with tumour angiogenesis." (PMID 30862840, 2019). "Likewise, the constitute production of TNF- α, will be associated with tumour prognosis." (PMID 31350970, 2019). "In addition, elderly tumor-associated CD11c+ cells may be further skewed toward suppressive function due to increased IL-10 and TNF-α." (PMID 30560130, 2018). "These immunosuppressive features of TNFα were associated with chronic and prolonged exposure to the cytokine In a recent preclinical study, TNFα blockade was shown to significantly enhance tumor immunity and overcome resistance to anti–PD-1 and adoptive T cell therapy." (PMID 30305177, 2018). "In addition, IL-6 and TNF-α are conductor cytokines that mediate and have multiple physiological functions in various pathogenic inflammatory diseases, where they are involved in tumor progression, angiogenesis, and migration." (PMID 30034291, 2018). "Conceivably, the prolonged and consistent induction of pro-inflammatory molecules such as COX-2 and TNF-α could lead to chronic inflammation and damage in the lung tissues and such condition, mimicking smoking, could favor tumor development in MGL-deficient lung tissues." (PMID 29348400, 2018). "Notably, consistent with enhanced recruitment of tumor-associated macrophages (TAMs) to tumors observed in vivo, ELISA analysis revealed a significant increase in the production of TNFα in the co-culture system in the presence of GDC-0941 when compared to the vehicle control." (PMID 30042442, 2018). "Moreover, signaling in MSCs via TNFα and TGFβ1 has been strongly associated with tumor progression." (PMID 28553282, 2017). "On the other hand, IL-10, IL-17 and TNFα, though some studies indicate that they activate cell growth, they have been associated with blocking apoptosis, inhibiting antigen presenting cells, inhibiting cytokine production, favour tumor growth and promote inflammation." (PMID 29246138, 2017). "Thus the release of CXCL8 from the PTEN-deficient tumor cells may also potentiate the IR-induced, macrophage-derived elevation of TNF-α signaling within the microenvironment of PTEN-deficient tumors." (PMID 26799286, 2016). "Interestingly, we observed several pro-inflammatory cytokines such as IL-17A, IL-6 and TNF-α that were downregulated (at an mRNA level) in mda-9-deficient naïve lungs, suggesting a potential impairment of pro-tumorigenic responses to invading tumor cells." (PMID 27341128, 2016). "In addition, we also characterized whether the secretion of CXCL8 from PTEN-deficient tumor cells may affect the level of macrophage-derived TNF-α secretion." (PMID 26799286, 2016). "Consequently, the intravenous administration of LF- and LFC-bearing, TNFα-encoding dendriplexes led to a sustained inhibition of tumor growth and even tumor suppression for 40% of the A431 tumors and up to 50% of the B16-F10 tumors, with long-term survival of the animals." (PMID 25933695, 2015). "However, TNFα has also been implicated in anti-tumor activities." (PMID 23965971, 2013).
tumor (continued). "Tumour necrosis factor-alpha (TNF-α) and nuclear factor of kappa light chain gene enhancer in activated B cells (NF-κB) are two major mediators of inflammation in cancer and they are intricately linked to malignant processes like tumour initiation, proliferation, invasion and angiogenesis." (PMID 24324738, 2013). "On the other hand, tumor growth may be associated with the progressive inhibition of NF-κB and in the progressive development of M2 inflammation, characterized by low levels of TNF-α, IL-1, and IL-12, and high levels of IL-10 and TGF-β." (PMID 23691510, 2013). "In the present study we show that loss of the tumor suppressor Smad4 may be one of the molecular mechanisms that can lead to this relative overexpression of the laminin-γ2 chain in response to the inflammatory cytokine TNFα." (PMID 20307265, 2010). "Indeed, these observations presented the possibility that tumor development may be associated to the genetic predisposition of the host to produce higher levels of TNF-α." (PMID 16438713, 2006). "The suppression of tumor growth could be also explained by intracellular effects causing apoptosis presumably by a mitochondria cytochrome c-dependent apoptotic mechanism, reduction of the TNFα and VEGF production on malignant tumor cells." (PMID 16796759, 2006). "Immune cell infiltration, such as macrophages, releases proinflammatory cytokines (IL-6, IL-17, TNF-α), which enhance tumor proliferation, survival, and invasion." (PMID 41438576, 2026). "After NIR treatment, the expression level of TNF-α increased, which was attributed to the benifical photothermal effect of CoS precipitate to further kill tumour cells." (PMID 41484054, 2026). "TNF-α (as a pro-inflammatory cytokine), can act either as a promoter of cancer or a tumor suppressor." (PMID 41488204, 2026). "TNF‐α induces drug‐resistant status in multiple types of cancers to prolong the survival of tumor cells exposed to Cisplatin." (PMID 40968783, 2026). "RT-qPCR analysis demonstrated upregulation of anti-tumor inflammatory cytokines (IL-6, TNF-α, iNOS) and concurrent downregulation of pro-tumor factors (IL-4, IL-10), confirming successful M2 to M1 phenotype conversion with efficacy comparable to LPS treatment." (PMID 41560805, 2026). "TNF-α occupies a central position in the inflammatory tumour microenvironment, where chronic signalling through TNFR1 typically activates NF-κB mediated pro-survival programmes rather than apoptotic cascades." (PMID 41596561, 2026). "By depleting intracellular zinc in cancer cells, they rapidly degrade IAPs and restore the caspase pathway, sensitizing tumor cells to TNF-induced killing." (PMID 41355954, 2026). "Tumor volume and morphological changes in various organs were observed, and the serum concentrations of IL-6, IL-10, and TNF-α were assessed." (PMID 41901226, 2026). "Levels of TNFα were also further increased by 18 months of age in tumor-free mice, consistent with a chronic inflammatory phenotype observed in caspase-2-deficient mice." (PMID 41477850, 2026). "The generated CoS precipitate had a strong photothermal effect, which further killed the tumour and promoted the increase of TNF-α." (PMID 41484054, 2026). "Tumor growth, gene expression of Per1, Per2, Per3, and Rev-Erbα, and TNF-α concentrations were analyzed at six circadian time points." (PMID 41736190, 2026). "This drives M2-like polarization and Smad2-mediated transcription of tumor necrosis factor-α (Tnf-α), which activates Nf-κB in neighboring tumor cells, conferring chemoresistance." (PMID 41975075, 2026). "AP1S1 showed enrichment for IL6-JAK-STAT3 and TNFα-NFκB signaling, as well as apoptosis and G2/M checkpoint pathways, suggesting involvement in both metabolic regulation and tumor-immune interactions." (PMID 41438582, 2026). "IL-37 suppresses many pro-inflammatory pathways, including NF-κB, MAPK, and the cytokines IL-1β, IL-6, and TNF, thereby inhibiting tumor growth." (PMID 41596472, 2026).